KIF24 (kinesin family member 24)
Description:
Microtubule-dependent motor protein that acts as a negative regulator of ciliogenesis by mediating recruitment of CCP110 to mother centriole in cycling cells, leading to restrict nucleation of cilia at centrioles. Mediates depolymerization of microtubules of centriolar origin, possibly to suppress aberrant cilia formation. Following activation by NEK2 involved in disassembly of primary cilium during G2/M phase but does not disassemble fully formed ciliary axonemes. As cilium assembly and disassembly is proposed to coexist in a dynamic equilibrium may suppress nascent cilium assembly and, potentially, ciliar re-assembly in cells that have already disassembled their cilia ensuring the completion of cilium removal in the later stages of the cell cycle. Plays an important role in recruiting MPHOSPH9, a negative regulator of cilia formation to the distal end of mother centriole.
Synonyms: C9orf48; bA571F15.4; FLJ10933; FLJ43884
Tractability: PROTAC: ubiquitination databases record sites on it.
Target class: Other cytosolic protein
Gene: Protein-coding gene on chromosome 9 (34,252,380 to 34,329,280, reverse strand). Ensembl gene ENSG00000186638.
Subcellular location: Cytoplasm, cytoskeleton, microtubule organizing center, centrosome, centriole; Cytoplasm, cytoskeleton, microtubule organizing center, centrosome
Pathways (Reactome):
Organelle biogenesis and maintenance: Anchoring of the basal body to the plasma membrane
Gene Ontology:
Molecular function: identical protein binding; microtubule motor activity; protein binding; ATP binding; microtubule binding
Biological process: cilium assembly; microtubule depolymerization; negative regulation of cilium assembly; microtubule-based movement
Cellular component: centriole; centrosome; protein-containing complex; cytosol
Genetic constraint (gnomAD): Loss-of-function variants: 52 observed, 89.56 expected, observed/expected ratio (o/e) 0.58, 90% interval 0.46 to 0.73. The upper end of that interval is the gene's LOEUF score, 0.73, which puts it in group 2 of 6, group 1 being the genes least tolerant of losing a copy. Missense variants: 1,323 observed, 1,485.3 expected, observed/expected ratio (o/e) 0.89, 90% interval 0.85 to 0.93. Synonymous variants: 527 observed, 556.09 expected, observed/expected ratio (o/e) 0.95, 90% interval 0.88 to 1.02.
Homologues: Orthologues: chimpanzee KIF24 (99% identical), macaque KIF24 (95% identical), dog KIF24 (78% identical), rabbit KIF24 (74% identical), mouse Kif24 (72% identical), pig KIF24 (72% identical), rat Kif24 (71% identical), Drosophila melanogaster Klp10A (16% identical), Drosophila melanogaster Klp59D (15% identical), Drosophila melanogaster Klp59C (14% identical), Caenorhabditis elegans klp-7 (14% identical). Paralogues in human: KIF2A (18% identical), KIF2C (18% identical), KIF2B (15% identical), KIF13B (14% identical), KIF14 (14% identical), KIF1A (14% identical), KIF21B (14% identical), KIF1B (14% identical), KIF21A (14% identical), CENPE (13% identical), KIF19 (13% identical), KIF13A (13% identical), and 29 more.
Diseases named in the same sentence as KIF24 in open-access papers:
KIF24 is named in the same sentence as 14 diseases in open-access papers, as found by Europe PMC text mining. Sharing a sentence is not in itself a finding about the gene and the disease. The quoted sentences say what the papers report.
breast carcinoma (3 papers, 2015 to 2020). "Knocking down of KIF2C, KIF3C, KIF22, KIF18A and KIF24 inhibited proliferation of breast cancer cells via different mechanisms including G2/M phase arrest, delayed exit from mitosis, deregulating cell division and restoring ciliation." (PMID 32322170, 2020). "Further, Nek2 and Kif24 are overexpressed in breast cancer cells, and ablation of these proteins restores ciliation in these cells, thereby reducing proliferation." (PMID 26290419, 2015). "By normalizing the expression profiles of Kif24 and Nek2 with HMECs, we found that Kif24 protein levels were comparable or modestly elevated across the panel of cell lines, whereas Nek2 was strongly upregulated (∼5–30-fold) in all breast cancer cell lines that we examined." (PMID 26290419, 2015). "Finally, we found that depletion of either Nek2 or Kif24 in breast cancer cell lines restored ciliation and reduced proliferation of these cells." (PMID 26290419, 2015). "Furthermore, abrogating this defective Nek2/Kif24 activation can restore primary cilia formation and restrict proliferation in breast cancer cells." (PMID 26290419, 2015). "Therefore, we compared the expression levels of Kif24 and Nek2 in a panel of breast cancer cell lines with the normal human mammary epithelial cell line (HMEC) as control." (PMID 26290419, 2015).
Cognitive impairment (1 paper, 2021). Abnormal cognition is characterized by deficits in thinking, reasoning, or remembering. "Interestingly, the patients of the MNI cohort carrying mutations affecting the motor domain of KIF24 protein showed mild-severe cognitive impairment (MoCA score ranging from 13 to 23)." (PMID 34148545, 2021).
Frontotemporal Lobar Degeneration (1 paper, 2021). "Single Nucleotide Polymorphisms (SNPs) located in the KIF24 gene have been associated to Frontotemporal Lobar Degeneration (FTLD)." (PMID 34148545, 2021).
situs inversus (1 paper, 2022). A congenital condition in which there is complete right-to-left reversal of the position of the major thoracic and abdominal organs (that is, they are arranged in a mirror image of the normal positioning). "Several differences can, however, be noticed, including the presence of situs inversus and polydactyly in the mouse model not observed in the affected fetuses with KIF24 variant." (PMID 35748595, 2022).
spondylometaphyseal dysplasia (1 paper, 2022). Spondylometaphyseal dysplasias are a heterogeneous group of disorders associated with walking and growth disturbances that become evident during the second year of life. "Altogether, our data implicate missense variations in KIF24 as a cause of a wide spectrum of skeletal ciliopathies ranging from a fetal skeletal ciliopathy to acromesomelic skeletal dysplasia and a less severe spondylometaphyseal dysplasia." (PMID 35748595, 2022).
tumor (3 papers, 2020 to 2022). "Next, tumor formation in KIF24-mutated Panc1 cells was evaluated in a mouse xenograft model." (PMID 35803737, 2022). "The tumor development also occurred earlier with KIF24-depleted cells than with control cells in vivo (4–6 wk after injection), suggesting that the mitotic effect of KIF24 depletion promotes the tumor onset." (PMID 35803737, 2022). "As more primary cilia were assembled in the excised tumors than in the cultured cells (∼25% in Kif24-3 tumor slices), it is plausible that these organelles opposed the long-term in vivo growth of Kif24-3 cells." (PMID 35803737, 2022). "Alternatively, aneuploidy provoked by chromosome mis-segregation in Kif24-3 cells may result in heterogeneous populations of cells with diverse proliferative profiles during long-term tumor growth." (PMID 35803737, 2022). "Interrogating published expression datasets against our SMG list found KIF24, KCNK5, EPB41L2, and ABI3BP downregulated in AK compared with those in the normal skin, suggesting tumor suppressor roles." (PMID 33482222, 2021). "In AK versus normal skin, five SMGs were significantly downregulated in at least two datasets (KIF24, KCNK5, EPB41L, INSIG2, and ABI3BP), suggesting a tumor suppressor role." (PMID 33482222, 2021).
cancer (2 papers, 2021 to 2022). A tumor composed of atypical neoplastic, often pleomorphic cells that invade other tissues. "Based on our study, potentiation of the mitotic activity of KIF24 could be a valid intervention strategy for PDAC, although we need to consider that loss of primary cilia by KIF24 might aggravate this cancer at present." (PMID 35803737, 2022). "We found that CP110 levels were not altered in Kif24-3 cells, suggesting that, like in U2OS cells, CP110-dependent centriolar events are not affected by KIF24 depletion in Panc1 cancer cells." (PMID 35803737, 2022).
infection (1 paper, 2020). The state of being infected such as from the introduction of a foreign agent such as serum, vaccine, antigenic substance or organism. "Multiple kinesin motors, including KIF24, are required for the formation of Salmonella-induced filaments during infection by Salmonella enterica." (PMID 32781641, 2020).
skeletal dysplasia (1 paper, 2022). Any Mendelian diseases that affects growth and development of the skeleton. "In conclusion, our study describes novel forms of skeletal dysplasia associated with biallelic variants in KIF24." (PMID 35748595, 2022).
KIF24 also shares sentences with these, for which no sentence is quoted: acromesomelic dysplasia (1 paper); bone disorder (1); genetic diseases (1); medulloblastoma (1); triple-negative breast carcinoma (1).